ALKAL1 (ALK and LTK ligand 1)
Description:
Cytokine that acts as a physiological ligand for receptor tyrosine kinase LTK, leading to its activation. Monomeric ALKAL1 binds to LTK, leading to LTK homodimerization and activation. In contrast to ALKAL2, does not act as a potent physiological ligand for ALK.
Synonyms: FAM150A; UNQ9433; AUGB; AUGA
Tractability: Antibody: UniProt places it where antibodies can reach, with high confidence; its Gene Ontology location is reachable by antibodies, with high confidence; UniProt predicts a signal peptide or a membrane-spanning region.
Gene: Protein-coding gene on chromosome 8 (52,534,037 to 52,565,430, reverse strand). Ensembl gene ENSG00000196711.
Subcellular location: Secreted; Cell membrane
Pathways (Reactome):
Signal Transduction: Signaling by ALK; Signaling by LTK
Gene Ontology:
Molecular function: cytokine activity; protein binding; receptor signaling protein tyrosine kinase activator activity; receptor tyrosine kinase binding
Biological process: cell surface receptor protein tyrosine kinase signaling pathway; positive regulation of ERK1 and ERK2 cascade; positive regulation of ERK5 cascade; positive regulation of neuron projection development
Cellular component: extracellular region; plasma membrane
Genetic constraint (gnomAD): Loss-of-function variants: 11 observed, 6.83 expected, observed/expected ratio (o/e) 1.61, 90% interval 0.96 to 1.94. That is too few expected variants to judge how well the gene tolerates losing a copy. Missense variants: 143 observed, 95.38 expected, observed/expected ratio (o/e) 1.5, 90% interval 1.31 to 1.72. Synonymous variants: 72 observed, 43.76 expected, observed/expected ratio (o/e) 1.65, 90% interval 1.36 to 1.92.
Homologues: Orthologues: chimpanzee ALKAL1 (99% identical), macaque ALKAL1 (95% identical), rabbit ALKAL1 (86% identical), pig ALKAL1 (75% identical), dog ALKAL1 (74% identical), mouse Alkal1 (72% identical), rat Alkal1 (72% identical), zebrafish alkal1 (47% identical), tropical clawed frog alkal1 (47% identical).
Diseases named in the same sentence as ALKAL1 in open-access papers:
ALKAL1 is named in the same sentence as 10 diseases in open-access papers, as found by Europe PMC text mining. Sharing a sentence is not in itself a finding about the gene and the disease. The quoted sentences say what the papers report.
colorectal cancer (1 paper, 2021). A primary or metastatic malignant neoplasm that affects the colon or rectum. "In the current study, we give an update on what we know so far of ALKAL1 in colorectal cancer progression." (PMID 33391411, 2021). "Our findings reveal a new mechanism by which ALKAL1 participates in colorectal cancer migration and invasion via activating the SHH signaling pathway." (PMID 33391411, 2021). "Herein, we analyzed colorectal cancer RNA sequencing datasets from The Cancer Genome Atlas (TCGA) and found that ALKAL1 expression was upregulated in colorectal cancer tissues compared with adjacent normal tissues." (PMID 33391411, 2021). "Taken together, our results uncover a novel mechanism of ALKAL1 contributing to the activation of SHH signaling pathway in colorectal cancer progression." (PMID 33391411, 2021). "In vitro and in vivo assays were performed to assess the biological roles of ALKAL1 in colorectal cancer." (PMID 33391411, 2021). "Herein, we analyzed colorectal cancer RNA sequencing datasets from TCGA and found that ALKAL1 high expression also significantly and positively correlated with PTCH protein levels." (PMID 33391411, 2021). "Statistical analysis was performed to explore the correlation between ALKAL1 expression and clinicopathological features in colorectal cancer." (PMID 33391411, 2021). "In summary, our findings reveal that ALKAL1 plays an important role in colorectal cancer migration and invasion via activating SHH signaling pathway." (PMID 33391411, 2021). "Our results found that ALKAL1 was dramatically elevated in colorectal cancer tissues compared to the adjacent normal tissues and high expression of ALKAL1 correlated with poor prognosis in colorectal cancer patients." (PMID 33391411, 2021). "To determine the biological roles of ALKAL1 in colorectal cancer, we constructed ALKAL1 silencing RKO and SW480 cell lines by endogenously knocking down ALKAL1 with retrovirus (sh.#1 and sh.#2) infection." (PMID 33391411, 2021). "Results showed that ROCK1, LIMK1, MMP3, and MMP9 mRNA expressions were down-regulated after ALKAL1 silencing in colorectal cancer RKO and SW480 cells." (PMID 33391411, 2021). "To investigate the effects of ALKAL1 on the tumorigenic activity of colorectal cancer cells, we performed an anchorage-independent growth assay and found that ALKAL1 silencing reduced the anchorage-independent growth ability of colorectal cancer cells." (PMID 33391411, 2021). "To investigate the effects of ALKAL1 on the metastatic ability of colorectal cancer cells, we performed cell wound healing and migration assay and found ALKAL1 silencing reduced the migration ability of colorectal cancer cells." (PMID 33391411, 2021). "Moreover, ALKAL1 silencing inhibited tumorigenesis, migration and invasion of colorectal cancer cells." (PMID 33391411, 2021). "In this study, we found that ALKAL1 was upregulated in colorectal cancer tissues and cell lines." (PMID 33391411, 2021). "As a result, we showed that ALKAL1 was upregulated in colorectal cancer tissues and cell lines." (PMID 33391411, 2021). "In here, we give an update on what we know so far of ALKAL1 in colorectal cancer progression." (PMID 33391411, 2021). "We further examined the role of ALKAL1 in SHH signaling pathway in colorectal cancer cells." (PMID 33391411, 2021). "Upregulation of ALKAL1 correlated with tumor malignancy and poor prognosis in colorectal cancer." (PMID 33391411, 2021). "Similarly, transwell cell invasion and migration assay also showed that downregulating ALKAL1 decreased the invasion and migration ability of colorectal cancer cells." (PMID 33391411, 2021). "However, the role and molecular mechanisms of ALKAL1 in colorectal cancer are still poorly understood." (PMID 33391411, 2021). "Therefore, improved understanding of the specific role of ALKAL1 in the pathogenesis of colorectal cancer facilitates to increase our knowledge in colorectal cancer development." (PMID 33391411, 2021).
colorectal cancer (continued). "Notably, RKO and SW480 cells that highly expressed ALKAL1 are cell lines derived from patients with poorly differentiated colorectal cancer." (PMID 33391411, 2021). "In addition, high expression of ALKAL1 was observed in 207/377 colorectal cancer tissue samples." (PMID 33391411, 2021). "However, due to its poor stability, the underlying mechanisms of ALKAL1 regulatingthe tumor progression in the human cancers including colorectal cancer have not been well documented." (PMID 33391411, 2021). "However, due to its poor stability, the mechanisms of ALKAL1 underlying the tumor progression in the human cancers including colorectal cancer have not been well documented." (PMID 33391411, 2021). "ALKAL1 silencing inhibited tumorigenesis, metastasis and invasion of colorectal cancer cells, and inhibited SHH signaling pathway, which is essential for ALKAL1 induced migration." (PMID 33391411, 2021). "Especially ALKAL1 showed high level expression in DLD-1, HCT-8, LS 174T, RKO, SW480 and SW620 cell lines, when compared with colorectal normal cell lines (CECs and RECs) or colorectal cancer Caco-2 or T84 cell lines." (PMID 33391411, 2021). "Furthermore, ALKAL1 silencing inhibits migration and invasion, and SHH signaling pathway of colorectal cancer cells." (PMID 33391411, 2021). "However, the specific mechanism responsible for the improved outcomes in colorectal cancer patients with high ALKAL1 expression, the biological role of ALKAL1 overexpressing in colorectal cancer cell lines and the targets of ALKAL1 in SHH signaling pathway were not mentioned in this manuscript." (PMID 33391411, 2021).
cancer (5 papers, 2014 to 2025). A tumor composed of atypical neoplastic, often pleomorphic cells that invade other tissues. "Activation of Anaplastic lymphoma kinase (ALK) and leukocyte tyrosine kinase (LTK) by their cognate cytokines ALKAL2 and ALKAL1 plays important roles in development, metabolism, and cancer." (PMID 40208865, 2025). "The HE staining results showed that the ability of ALKAL1-silenced cancer cells in the tumor of mice to invade surrounding cells was significantly reduced." (PMID 33391411, 2021). "In addition to these, we also identified some novel genes among the 14-CpG markers that were not previously associated with cancer recurrences such as IFFO1, ALKAL1, FAHD1, FSTL4, SLC7A9, IQCJ-SCHIP1, CLDN11 and three other CpGs at intergenic regions." (PMID 34207933, 2021).
tumor (3 papers, 2021 to 2025). "Gene set enrichment analysis (GSEA), Western blotting and luciferase assays were used to identify the underlying signal pathway involved in the tumor progression role of ALKAL1." (PMID 33391411, 2021). "High expression of ALKAL1 was strong positive correlated with tumor classification, node classification and pathological stages." (PMID 33391411, 2021). "As a result, we found that the tumors formed by the ALKAL1-silenced cells were smaller, and the tumor volumes and weight were decreased significantly in the ALKAL1 silencing group compared with the control group." (PMID 33391411, 2021). "Therefore, whether ALK activation mediated by ALKAL1/2 contributes to tumor progression still needed to be confirmed by further studies." (PMID 40246819, 2025).
ALKAL1 also shares sentences with these, for which no sentence is quoted: neuroblastoma (3 papers); infection (2); autoimmune disease (1); clear cell carcinomas (1); lung carcinoma (1); pancreatic adenocarcinoma (1); pancreatic cancer (1).